WNT10A (Wnt family member 10A)
Diseases named in the same sentence as WNT10A in open-access papers (continued):
Sharing a sentence is not in itself a finding about the gene and the disease.
Oligodontia (24 papers, 2013 to 2025). The absence of six or more teeth from the normal series by a failure to develop. "It has been reported that over 50% of oligodontia probands have WNT10A mutations; according to a population-based cohort study, approximately 28% of oligodontia probands have WNT10A mutations." (PMID 39941240, 2025). "In this study, genes associated with oligodontia (MSX1, PAX9, AXIN2, and WNT10A) were analyzed in both the patient and her relatives with oligodontia, revealing the same mutation in the initial codon of the PAX9 gene." (PMID 40692763, 2025). "The proband also carried a heterozygous WNT10A variant (NM_025216.3:c.637G>A p.(Gly213Ser)), which is pathogenic in autosomal recessive oligodontia caused by WNT10A mutations." (PMID 39685785, 2024). "Missense variants (c.1138A>C) and (c.511C>T) in EDAR and WNT10A, respectively, have been previously reported in oligodontia patients." (PMID 37745851, 2023). "Similar to Wnt10A, genetic mutations in Wnt10B have been found in dental anomalies, such as TA and oligodontia." (PMID 36982827, 2023). "Mutations in WNT10A account for more than half of the isolated hypodontia and oligodontia cases and have been identified with odonto-onycho-dermal dysplasia." (PMID 36982827, 2023). "We consider this variant as likely pathogenic acting dominantly with reduced penetrance, given that the patient's mother is a carrier for a WNT10A variant and there is a family history of oligodontia (Family 2)." (PMID 37361548, 2023). "Seventy-four isolated oligodontia cases and twenty-eight syndromic oligodontia cases with WNT10A gene mutations (102 total) were analyzed." (PMID 34593752, 2021). "Two probands with severe oligodontia carried not only LRP6 mutations but also WNT10A pathogenic variants, suggesting a potential mutational synergism or digenic inheritance for WNT signaling-related genes in FTA." (PMID 34834569, 2021). "In our study, ED is the most frequently mentioned syndrome with oligodontia, while WNT10A mutations constitute the most frequently determined genetic cause, 53.84%, of the syndromic oligodontia." (PMID 34593752, 2021). "This study presents clinical, radiological and genetic evaluations of a familial non-syndromic oligodontia caused by variation on WNT10A gene." (PMID 32618450, 2020). "The present findings have provided evidence for a known variant in the WNT10A gene in a three-generation consanguineous family with isolated oligodontia, while the results confirmed that cases with homozygous mutation revealed clinical hetero­geneity." (PMID 32618450, 2020). "In accordance with the previous reports, the present findings support the association between WNT10A mutation and non-syndromic oligodontia." (PMID 32618450, 2020). "We identified a novel compound heterozygous missense mutation in WNT10A (c.637G>A:p.Gly213Ser and c.1070C>T:p.Thr357Ile) as the likely cause of autosomal recessive oligodontia in the child." (PMID 29178643, 2017). "We investigated seven individuals with severe oligodontia for their primary dentition, presence of ectodermal symptoms and WNT10A mutations." (PMID 27881089, 2016). "Studies of patients with non-syndromic oligodontia (agenesis of 6–28 teeth) referred for centralized treatments revealed a carrier frequency of up to 56% for WNT10A mutations." (PMID 27881089, 2016). "In isolated oligodontia, a great proportion (up to 54 %) of the cases are associated by WNT10A mutations." (PMID 26964878, 2016). "Altogether we detected heterozygous genotypes of these variants of WNT10A in 15 probands, 13 of whom classified as oligodontia." (PMID 23991204, 2013). "Therefore, this study aimed to analyze the WNT10A mutation, which is considered the most prevalent gene in oligodontia." (PMID 39941240, 2025). "In our study, 53.84% of syndromic oligodontia cases were caused by WNT10A mutations." (PMID 34593752, 2021). "Genetic alterations in EDA and WNT10A cause particularly non-syndromic/isolated oligodontia." (PMID 31652981, 2019).
Oligodontia (continued). "We have identified a novel missense variant (c.311G>A; p.Arg104His) in WNT10A in three oligodontia patients of family A, two novel sequence variants (c.207delinsTT, p.Gly70Trpfs*25 and c.1300T>G; p.Try434Gly) in EDAR in three patients of family B and four patients of family C, respectively." (PMID 31652981, 2019). "Taken together, independent reports from us and others indicate that WNT10A mutations are the most frequent specific cause of isolated hypodontia (agenesis of at least one tooth), and oligodontia (agenesis of six or more teeth, third molars excluded) of the permanent dentition known to date." (PMID 27881089, 2016). "Moreover, the same gene might be responsible for multiple conditions, such as a WNT10A variant, which can result in oligodontia, ectodermal dysplasia, or more severe syndromes." (PMID 37361548, 2023). "Our results reveal a novel compound heterozygous variant in WNT10A as pathogenic for oligodontia, and demonstrate that perturbations of wnt10a expression in zebrafish may directly and/or indirectly affect tooth development recapitulating the agenesis phenotype observed in humans." (PMID 29178643, 2017). "HED is the most frequently mentioned syndrome with oligodontia, while EDA and WNT10A mutations constitute the most frequently determined genetic cause: 30.4% of the syndromic oligodontia." (PMID 38132417, 2023). "The identified novel missense variants in WNT10A (c.311G>A; p.Arg104His) and EDAR (c.1300T>G; p.Trp434Gly) are assumed to cause autosomal recessive oligodontia and autosomal recessive HED." (PMID 31652981, 2019). "Mutations in numerous genes including msh homeobox 1 (MSX1), paired box 9 (PAX9), Wnt family member 10A (WNT10A), axis inhibition protein 2 (AXIN2), ectodysplasin A (EDA), and Wnt family member 10B (WNT10B) have been associated with nonsyndromic oligodontia." (PMID 30134957, 2018). "WNT10A mutation was reported to cause odonto-onycho-dermal dysplasia (OODD), a form of ED characterized by severe oligodontia, nail dystrophy, palmoplantar hyperkeratosis, and hyperhidrosis." (PMID 27657131, 2016). "We consider OODD, HED and oligodontia represented the full clinical manifestations of WNT10A-related ED." (PMID 27657131, 2016). "Noteworthy, mutations in the WNT co-receptor LRP6 gene were recently identified in rare cases of isolated oligodontia bringing further evidence for the importance of WNT10A in tooth development." (PMID 27881089, 2016). "We found biallelic genotypes of WNT10A in 11 probands, corresponding to 8.4% of all probands, and 13% of those with a phenotype defined as oligodontia." (PMID 23991204, 2013). "In humans, mutations in WNT10A are the most commonly reported in the genetic etiology for syndromic oligodontia, and PAX9 mutations are the most commonly reported genetic etiology for isolated oligodontia." (PMID 38132417, 2023). "Another patient presenting with isolated oligodontia with congenital absence of seven teeth and thin hair was found to have a heterozygous variant in the WNT10A gene (NM_025216.3: c.511C > T; p.Arg171Cys)." (PMID 37361548, 2023). "WNT10A mutations are the most commonly reported in the genetic etiology for syndromic oligodontia and PAX9 mutations are the most commonly reported genetic etiology for isolated oligodontia." (PMID 34593752, 2021). "Our results suggest that WNT10A and EDA digenic mutations could result in oligodontia and syndromic tooth agenesis in the Chinese population." (PMID 24312213, 2013). "However, a population-based study of Swedish individuals with isolated oligodontia revealed that the frequency of at least one WNT10A mutation in non-related probands was 28%." (PMID 27881089, 2016). "In the present study, we investigated six genes (MSX1, PAX9, AXIN2, WNT10A, EDA and EDARADD) in a patient with sporadic non-syndromic oligodontia." (PMID 26406231, 2015).
ectodermal dysplasia (23 papers, 2015 to 2024). "Mutations in WNT10A are associated with ectodermal dysplasias, such as odonto-onycho-dermal dysplasia, as well as tooth agenesis due to the important role of WNT10A in odontoblast differentiation." (PMID 35052478, 2022). "On the other hand, biallelic WNT10A mutations were first identified in patients with syndromes of ectodermal dysplasia, Schopf–Schulz–Passarge syndrome (SSPS, OMIM#224750), and odontoonychodermal dysplasia (OODD, OMIM#257980)." (PMID 34834569, 2021). "The ectodermal dysplasias resulting from biallelic mutations in the WNT10A gene result in highly variable phenotypes, ranging from isolated tooth agenesis to OODD and Schöpf-Schulz-Passarge syndrome (SSPS)." (PMID 26964878, 2016). "WNT10A was identified as a causal gene of autosomal recessive ectodermal dysplasia or isolated tooth agenesis." (PMID 26406231, 2015). "Although functional null variants of the WNT10A gene cause autosomal recessive ectodermal dysplasia, patients with a heterozygous null variant of the WNT10A gene are often diagnosed with nonsyndromic tooth agenesis but rarely with mild ectodermal dysplasia." (PMID 38263268, 2024). "Furthermore, WNT10A is associated with hypohidrotic ectodermal dysplasia, which is usually inherited in an X‐linked form and features light pigmentation." (PMID 35505885, 2022). "It has been confirmed that WNT10A mutation plays an important role in tooth dysplasia and ectoderm dysplasia, and WNT10A is highly expressed in a variety of malignant tumors, such as thyroid cancer, ovarian cancer, esophageal squamous cell carcinoma, renal cell carcinoma, and colorectal cancer." (PMID 36605938, 2022). "The range of phenotypes that result from functional variation at this locus closely resembles the known acne susceptibility locus harbouring WNT10A, at which genetic variation influences acne risk, hair curl, male pattern baldness and Mendelian forms of ectodermal dysplasia." (PMID 35132056, 2022). "As observed in WNT-10a-associated ectodermal dysplasias, the ANp keratinocytes may contribute to PPK development as a consequence of dysregulated canonical Wnt signaling and, in turn, loss of cell polarity." (PMID 35854363, 2022). "WNT10A mutations account for 16% of hypohidrotic ectodermal dysplasias." (PMID 35351192, 2022). "Human WNT10A mutations are associated with dental defects and adult onset ectodermal dysplasia." (PMID 28589954, 2017). "A patient with ectodermal dysplasia (conical spaced teeth, delayed eruption of certain teeth, but with all teeth present), thin hair, and fragile dysplastic nails on both hands and feet was found to have a pathogenic homozygous variant on the WNT10A gene (c.321C > A)." (PMID 37361548, 2023). "Only four genes (EDA1, EDAR, EDARADD, and WNT10A) account for 90% of hypohidrotic/anhidrotic ectodermal dysplasia cases." (PMID 38347173, 2024). "Four genes (EDA, EDAR, EDARADD, WNT10A) account for 90% of hypoidrotic/anhidrotic ectodermal dysplasia cases." (PMID 34078430, 2021). "Dystrophic or otherwise abnormal nails were evident in 17 of 18 subjects with pathogenic WNT10A or GJB6 variants but in none of 161 children with EDA variants underlying X-linked hypohidrotic ectodermal dysplasia." (PMID 36421794, 2022). "As the clinical presentation of patients with the same genotype ranges from mild symptoms of ectodermal dysplasia to more severe syndromic manifestations, it is recently concluded that OODD and SSPS should be considered as variable expression of the same WNT10A genotype." (PMID 26964878, 2016). "Based on the information from OMIM (National Center for Biotechnology Information, Bethesda, MD, USA) and the latest update on ectodermal dysplasia clinical classification, WNT10A is not recommended as a candidate gene for HED." (PMID 27657131, 2016).
odonto-onycho-dermal dysplasia (18 papers, 2010 to 2026). A form of ectodermal dysplasia characterized by hyperkeratosis and hyperhidrosis of the palms and soles, atrophic malar patches, hypodontia, conical teeth, onychodysplasia, and dry and sparse hair. "Pathogenic WNT10A (MIM *606268) variants can be responsible for isolated tooth agenesis as well as for odonto-onycho-dermal dysplasia (OODD; MIM #257980) and Schöpf–Schulz–Passarge syndrome (SSPS; MIM #224750)." (PMID 36421794, 2022). "For WNT10A, there appears to be a direct connection to hair morphology: mutations in this gene are known to cause odonto-onycho-dermal dysplasia, which includes dry, misformed hair as a symptom." (PMID 20585627, 2010). "Moreover, Wnt10a is upregulated during HF development, and Wnt10a missense mutations have been associated with the human syndromes odonto-onycho-dermal dysplasia and Schöpf–Schulz–Passarge, both characterized for malformations in ectodermal structures." (PMID 25536657, 2014). "Odonto-onycho-dermal dysplasia (OODD) is a rare, autosomal recessive disorder caused by pathogenic variants in the WNT10A gene, which plays a crucial role in ectodermal tissue development, including teeth, hair, nails, and skin." (PMID 41970645, 2026). "Seven studies reported mutations in EDA or WNT10A in HED, Christ–Siemens–Touraine syndrome, tricho-odonto-onychodermal dysplasia, and odonto-onychodermal dysplasia." (PMID 38132417, 2023). "This overlapping of phenotypes was also a feature of WNT10A disease-causing variants which were identified in NSTA, HED, odontoonychodermal dysplasia (OODD; OMIM#257980) and Schopf–Schulz–Passarge syndrome (OMIM#224750)." (PMID 35741818, 2022). "In odonto-onychodermal dysplasia (OODD) patents, anodontia of permanent teeth is caused by the biallelic Wnt10A gene mutations." (PMID 34168671, 2021). "Another detected germline variant was a heterozygous WNT10A mutation, variant chr2:218882368C>A in gene WNT10A (ENST00000258411.8, c.321C>A, rs121908119), described as pathogenic in ClinVar and associated with Odonto-onycho-dermal dysplasia, tooth agenesis, and other phenotypes." (PMID 39768544, 2024). "Odonto-onycho-dermal dysplasia (OODD), another kind of STA characterized by massive loss of teeth, hyperhidrosis, palmoplantar hyperkeratosis, and nail dystrophy, is caused by mutations of WNT10A." (PMID 28981473, 2017).
breast carcinoma (10 papers, 2013 to 2024). "In mice with 4T1 tumors, we found significant reductions in both Wnt 4 and Wnt10A, genes encoding ligands that can activate downstream Wnt signaling, which has been linked to increased breast cancer metastasis." (PMID 39410010, 2024). "Little is known about the role of WNT10A in breast cancer but Wnt4 is essential for normal progesterone induced mammary gland development." (PMID 23861811, 2013). "Moreover, CARMN was found to control breast cancer stem cell self‐renewal by regulating wnt10a via the formation of functional triplex." (PMID 36578176, 2023). "WNT10A functions as an oncogene in renal cell carcinoma, whose depletion was reported to prevent tumor growth in vitro and in vivo in melanoma; however, it shows tumor suppressive roles in breast cancers in our study which worth further investigations." (PMID 31699026, 2019). "E2F1 and E2F4 induce whereas pRb/RBL2 reduce WNT ligand expression (e.g. WNT7A, WNT7B, WNT10A, WNT4) thereby regulating self-renewal, chemoresistance and invasiveness of CSCs in both PDAC and breast cancer, and fibroblast proliferation." (PMID 38678032, 2024). "In the 4T1 mouse model of breast cancer, the CLOCK component has been found to induce regular expression of Wnt family member 10A (Wnt10A) and upregulate the expression of downstream acetaldehyde dehydrogenase 3 (ALDH3A1)." (PMID 36647780, 2023). "In a breast cancer mouse model, CLOCK and BMAL1 in the TME promoted tumorigenesis and metastasis through the upregulation of WNT10A-mediated ALDH3A1 expression in cancer stem cells." (PMID 37524704, 2023). "Our present study is an extension of our previous work, in which we proposed the co-regulated expression pattern of the WNT gene cluster (WNT-1, WNT-6, WNT-10A and WNT-10B) in human breast carcinoma." (PMID 23372744, 2013). "A WNT receptor and a WNT ligand were also dysregulated in breast cancer cell lines, FZD4 showed higher expression in breast cancer cell lines whilst WNT10A expression was decreased." (PMID 23861811, 2013). "WNT ligands WNT1, WNT10a and WNT4 were expressed at higher levels in normal AR cells compared to monolayer cells, however in the breast cancer cell lines, their expression was lower in the AR cells compared to monolayer cells." (PMID 23861811, 2013).
Schöpf-Schulz-Passarge syndrome (8 papers, 2013 to 2023). "Moreover, decreased Wnt/β-catenin signaling due to WNT-10a loss-of-function mutations leads to a compensatory PPK as observed in odonto-onycho-dermal dysplasia and Schöpf-Schulz-Passarge syndrome." (PMID 35854363, 2022). "Also, multiple syringofibroadenomas on the palms and soles and multiple eyelid hidrocystomas are distinctive for Schöpf-Schulz-Passarge syndrome, the autosomal recessive disease caused by WNT10A (Wnt Family Member 10A) gene mutation." (PMID 34064849, 2021).
pulmonary fibrosis (7 papers, 2016 to 2023). Chronic progressive interstitial lung disorder characterized by the replacement of the lung tissue by connective tissue, leading to progressive dyspnea, respiratory failure, or right heart failure. "As a member of the canonical Wnt/β‐catenin pathway, Wnt10A overexpression is associated with poor survival in patients with idiopathic pulmonary fibrosis." (PMID 33417298, 2021). "To elucidate the mechanisms underlying the role of WNT10A in pulmonary fibrosis, we focused on collagen, one of the components of the extracellular matrix." (PMID 27071460, 2016). "Wnt10a, a Wnt ligand involved in pulmonary fibrosis 59, 60, was upregulated in the silica-treated group compared to that in the control group." (PMID 37063430, 2023). "Inhibition of Gli1 suppressed myofibroblast differentiation of LR-MSCs and pulmonary fibrosis, and decreased the expression of Wnt7b, Wnt10a and β-catenin." (PMID 29844390, 2018). "In this study, we evaluated the expression of WNT10A in the setting of bleomycin (BLM)-induced lung fibrosis in mice and assessed the interactions between TGF-β, BLM and WNT10A at sites of fibroblast cells in vitro." (PMID 27071460, 2016). "Our results show that the WNT10A expression therefore plays an important role in pulmonary fibrosis via TGF-β1 signaling." (PMID 27071460, 2016). "Therefore, WNT10A may represent a novel pathway contributing to the persisting phenotype of lung fibrosis." (PMID 27071460, 2016). "WNT/β-catenin signaling plays an important role in the pathogenesis of idiopathic pulmonary fibrosis (IPF); however, the role of WNT10A via transforming growth factor (TGF)-β signaling remains unclear." (PMID 27071460, 2016). "Although WNT signaling pathways have been shown to function in the setting of pulmonary fibrosis, the relationship with WNT10A is not well defined." (PMID 27071460, 2016). "Studies have also shown that WNT10A plays an important role in the pathogenesis of idiopathic pulmonary fibrosis via TGF-β activation and may be a sensitive predictor of the onset of an acute exacerbation of idiopathic pulmonary fibrosis." (PMID 36273119, 2022).